RNU1-114P (RNA, U1 small nuclear 114, pseudogene)
Gene: Small nuclear RNA gene on chromosome 1 (143,652,050 to 143,652,215, reverse strand). Ensembl gene ENSG00000202167.
Homologues: Orthologues: chimpanzee U1 (99% identical), dog U1 (69% identical), guinea pig U1 (67% identical), rabbit U1 (64% identical), dog U1 (62% identical), rabbit U1 (61% identical), dog U1 (60% identical), rabbit U1 (60% identical), dog U1 (59% identical), dog U1 (58% identical), rabbit U1 (54% identical). Paralogues in human: RNU1-129P (84% identical), RNU1-154P (84% identical), RNVU1-31 (72% identical), RNU1-1 (70% identical), RNU1-2 (70% identical), RNU1-27P (70% identical), RNU1-28P (70% identical), RNU1-3 (70% identical), RNU1-4 (70% identical), RNVU1-18 (70% identical), RNVU1-29 (70% identical), U1 (70% identical), and 133 more.